TLR9 (toll like receptor 9)
Diseases named in the same sentence as TLR9 in open-access papers (continued):
Sharing a sentence is not in itself a finding about the gene and the disease.
Obesity (continued). "In addition, work in Tlr9-/- mice showed a lower inflammatory response compared to wild-type mice fed a high-calorie diet and demonstrated the relationship between adipocyte degeneration, free DNA release, TLR9 activation, and the development of adipose tissue inflammation in an obesity background." (PMID 37569389, 2023). "AT-SRA1 expression was independently predicted by TLR3/TLR7 and IRAK1 in those with obesity and by TLR3/TLR9 in individuals with T2D." (PMID 36552771, 2022). "While we recently demonstrated a significant expression of functional TLR9 in adipocytes, only sparse data are available on the overall expression of TLR7 in adipocytes in obesity." (PMID 35955609, 2022). "Our data show strong positive correlations between adipose IRF5 gene expression and that of TLR2, TLR7, TLR8, TLR9, MyD88, IRAK-1, and IRF3 in obesity." (PMID 31718015, 2019). "Due to the important role of FFA in obesity-induced inflammation, we then investigated the FFA effects on TLR9/KLF4." (PMID 30662369, 2018). "The IKK/NF-κB pathway is a well-known inflammatory signaling pathway involved in the pathogenesis of obesity, and the two genes-PTGS2 and TLR9 involved in this enrichment term should also be focused." (PMID 29132311, 2017). "The magnitudes of the obesity-induced upregulation of the TLR1, TLR4, TLR5, TLR8, TLR9, and TLR12 genes in the visceral adipose tissue were even greater in the diet-induced obesity (DIO) mice than in the ob/ob mice." (PMID 26681840, 2015). "We found that, in the absence of Tlr9 specifically in B cells, B6 mice were prone to development of obesity with high fat diet, without an increase in food intake." (PMID 38762479, 2024). "B cells express high levels of TLR962,63; however, the role of TLR9 in B cells in the development of obesity has not previously been clear." (PMID 38762479, 2024). "In summary, our research has explored the molecular mechanism of the inhibition effect of TLR9/KLF4 on FFA-induced inflammatory response of adipocytes, which can help to elucidate the molecular mechanism of obesity initiating inflammation and to provide a new experimental basis." (PMID 30662369, 2018). "Conversely, administration of TLR9 antagonist (iODN2088) to HFD-fed mice attenuated metabolic tissue inflammation, improved glucose metabolism, and ameliorated manifestation of liver steatosis, confirming the crucial role of TLR9 in obesity-mediated pathogenesis." (PMID 33574823, 2020). "However, whether pDC-specific expression of TLR9 and production of IFN-I are directly involved in obesity-mediated metabolic syndromes in vivo require further investigation." (PMID 33574823, 2020). "Multiple TLRs, including TLR2, TLR3, TLR4, TLR5, TLR8, TLR9, and TLR10, have been indicated in the regulation of PAMPs from gut microbiota and DAMPs from metabolic stress and tissue damage, which initiate the inflammatory responses contributing to the development of obesity-related chronic diseases." (PMID 31582899, 2019).
influenza (27 papers, 2008 to 2025). An acute viral infection of the respiratory tract, occurring in isolated cases, in epidemics, or in pandemics; it is caused by serologically different strains of viruses (influenzaviruses) designated A, B, and C, has a 3-day incubation period, and usually lasts for 3 to 10 days. "In particular, the expression of Zdhhc9 was repressed during TLR9 sensing in GM‐DCs, but also when human pDCs were exposed to influenza." (PMID 40828036, 2025). "Synthetic unmethylated CpG oligonucleotides (CpG-ODN) are potent Toll-like receptor-9 (TLR-9) agonists that have strong adjuvant properties and have been shown to increase the efficacy of an influenza vaccine administered IN." (PMID 39293153, 2024). "To determine what role TLR recognition pathways play in the generation of the iABC response to influenza infection, we infected TLR7 and TLR9 deficient aged mice and compared their responses to WT aged and young mice at 14 dpi." (PMID 36056604, 2022). "Recently, a combination of MPL and CpG, a TLR9 agonist, immunized with influenza split vaccine elicited strong antigen-specific Th1 immune responses and induced protective efficacy against homosubtypic and heterosubtypic influenza infections." (PMID 34571785, 2021). "It has previously been reported in mice that specific ligands for TLR9 induced protection against influenza, and that TLR9 plays a protective role in the early stages of S. pneumoniae infection." (PMID 34644311, 2021). "TLR9 expression was reported to be elevated in monocytes and dendritic cells from influenza-infected patients compared to healthy individuals." (PMID 30682165, 2019). "Future work will be focused on elucidating the mechanism(s) of influenza-induced upregulation of TLR9 and the pathways which TLR9 alters to regulate MRSA killing." (PMID 30682165, 2019). "Changes in expression of different toll-like receptors (TLRs) (TLR2, TLR3, TLR4, TLR7, TLR8, and TLR9) have been reported before in human monocytes and dendritic cells from seasonal influenza infected patients." (PMID 30682165, 2019). "This is the first study of TLR9 regulation of influenza-bacterial superinfection and it highlights an unexpected pathologic role for TLR9 in regulating clearance of MRSA post-H1N1." (PMID 30682165, 2019). "Taken together these data show a surprising inhibitory role for TLR9 signaling in mediating clearance of MRSA that manifests following influenza infection." (PMID 30682165, 2019). "Adjuvants based on toll-like receptor agonists including TLR4 and TLR9 agonists used in pandemic and “universal” influenza vaccines, respectively, have shown excellent results in phase I trials." (PMID 29326687, 2017). "Here, we report that synthetic ligands for TLR2/6 and TLR9 induce robust protection against lethal influenza pneumonia, including from swine-origin H1N1 influenza." (PMID 22299046, 2012). "For instance, Class B CpG, a TLR9 agonist, is used as an adjuvant in influenza vaccines." (PMID 38003793, 2023). "Thus, unlike the progenitor ABC which develop independently of both foreign Ag and TLR7 and TLR9 pathways, the iABC response to influenza infection is highly dependent on both endosomal TLR7 and TLR9 pathways." (PMID 36056604, 2022). "Taken together, this suggests that TLR9 antagonism may be an effective therapeutic for MRSA complicated influenza infections assuming proper dosing can be identified." (PMID 30682165, 2019). "However, nothing is known about the role of other TLRs, including TLR9, in influenza-bacteria dual infection pathology." (PMID 30682165, 2019). "We tested whether stimulation of TLR7, the innate influenza sensor could lead to increased expression of TLR9 as it is known that NF-κB activation by TLRs can induce TLR expression." (PMID 30682165, 2019). "TLR3, TLR7, TLR9, and RIG1 are known to be involved in sensing influenza viral antigens and activating downstream signaling pathways." (PMID 39846844, 2025).
influenza (continued). "While mTOR is involved in the TLR9-induced type I interferon signaling pathway, and stimuli such as the TLR7-agonist gardiquimod or Influenza induce early glycolysis in pDCs, the effect of TLR4-ligands on the metabolism of pDCs is not well studied." (PMID 36059475, 2022). "Whole inactivated influenza virus (WIV) contains all influenza components including many B cell epitopes, and studies indicate they can stimulate TLR7 and TLR9." (PMID 36056604, 2022). "The response of ABC to influenza infection, resulting in iABC, is T cell independent and requires both extrinsic TLR7 and TLR9 signals." (PMID 36056604, 2022). "Here we show that expression of TLR9, a microbial DNA sensor, is increased in murine lung macrophages, dendritic cells, CD8+ T cells and epithelial cells post-influenza infection." (PMID 30682165, 2019). "Our findings confirm other studies in which pDCs were stimulated with influenza or West Nile Virus (TLR7), R848 (TLR7/8) or CpG (TLR9)." (PMID 31830086, 2019). "Poly (ICLC), a dsRNA, and CpG ODNs, molecular mimics for TLR3 and TLR9, respectively, have been reported to non-specifically stimulate the innate immune system and to provide protection against various bacterial and viral pathogens, including influenza." (PMID 19325820, 2008). "It has not yet been demonstrated whether influenza H5N1 affects TLR3/TLR9 signalling pathways." (PMID 19325820, 2008). "Treatment of mice with a TLR2/6 agonist (Pam2CSK4, “Pam2”) alone or a TLR9 agonist (ODN2395, “ODN”) alone resulted in no protection against lethal influenza pneumonia." (PMID 22299046, 2012).
Allergy (24 papers, 2007 to 2025). An allergy is an immune response or reaction to substances that are usually not harmful. "In clinical studies, TLR9 agonists had a good effect on the treatment of pathogenic infections, allergies and malignant neoplasms." (PMID 31166969, 2019). "The interaction of unmethylated CpG with mammalian immune cells through Toll-like receptor 9 (TLR9) forms the basis for effective adjuvants in treating immunologic and allergic diseases." (PMID 38542103, 2024). "The regulation of the immune system via the manipulation of TLR9 signaling by CpG ODNs is effective in infectious diseases, cancers, and allergy treatment." (PMID 37508406, 2023). "TLR-9 has immunomodulatory effects via increased Th1 and Treg cells, resulting in alleviation of allergic diseases." (PMID 32699202, 2020). "The ability of CpG (antigen that activates TLR9) to induce Th1 polarization made it an interesting new target for treating allergy and infectious diseases." (PMID 30802247, 2019). "The same TLR9-dependency in mediating Th2 responses was demonstrated in an OVA allergy model." (PMID 37426425, 2023). "DOCK8-deficient B cells show diminished responses to TLR9 signaling, suggesting a possible defect in IL-10-producing Breg cells in those with DOCK8 deficiency, which may contribute to allergies." (PMID 34867940, 2021). "Furthermore, other emerging data about TLR9 more generally offers compelling evidence for its role in modulation of inflammatory and allergic diseases, and a possible route to therapy." (PMID 21324137, 2011). "However, increasing evidence supports TLR9-based immunotherapy in allergic disorders, as shown in the prevention/treatment of experimental models of allergy." (PMID 19844589, 2009). "Furthermore, conventional IgE-mediated allergy responses have been shown to be dependent on TLR9." (PMID 29651299, 2018). "TLR9 enhances Th1 and Treg cell populations via IFN-γ, resulting in the prevention and treatment of allergic diseases." (PMID 32699202, 2020). "Unmethylated cytosine-guanine dinucleotide-containing oligodeoxynucleotide, as an agonist of Toll-like receptor 9 (TLR9), activates immune responses for use as vaccines to treat cancer, infectious diseases, and allergies." (PMID 28891335, 2017). "It has been previously shown that activation of MDSCs through either TLR9 or TLR4 can further differentiate MDSCs into a myeloid cell that no longer has tumor suppressor activity or Th2 allergy inducing polarization." (PMID 21966467, 2011).
liver fibrosis (23 papers, 2010 to 2025). "Hepatocyte-derived mtDNA during NASH is linked to sterile inflammation in a Toll-like receptor 9 (TLR9)-dependent manner, and was also shown to drive liver fibrosis by activating HSCs." (PMID 35855331, 2022). "TLR9- and MyD88- (adaptor molecule for TLR9) deficient mice have significantly lower insulin resistance and show less steatohepatitis and liver fibrosis histological pattern than WT mice." (PMID 27105827, 2016). "In addition, TLR9 is also involved in the development of liver fibrosis and its deficiency suppressed the progression of liver fibrosis in mice treated with CCl4." (PMID 33207562, 2020). "For instance, HSCs express functional TLR9, and its activation has been shown to exacerbate hepatic fibrosis by promoting pro-fibrotic responses." (PMID 40855408, 2025). "Tlr9−/− mice fed with a choline‐deficient L‐amino‐defined diet for induction of NAFLD show reduced steatohepatitis and liver fibrosis compared to WT mice, indicating that TLR9 is a driver for fatty liver disease." (PMID 39158380, 2025). "TLRs including TLR2, TLR3, TLR4 and TLR9 are expressed on hepatocytes, Kupffer cells, fibroblasts, neutrophils, dendritic cells and endothelial cells in the liver and activated in hepatic fibrosis liver tissue." (PMID 37122694, 2023). "In this study, we investigated the association between TLR9 rs5743836, rs352140, and rs187084 polymorphism and its plasma mRNA level in NAFL patients with different liver fibrosis scores compared to healthy controls." (PMID 36718239, 2022). "It has been demonstrated that tlr-9 knockout mice with a choline-deficient L-amino acid-defined (CDAA) diet are protected against lipid accumulation, steatohepatitis, and liver fibrosis through suppressing IL-1β production." (PMID 35165344, 2022). "In this study, we explored the association between TLR9 rs5743836, rs352140, and rs187084 polymorphism and its plasma mRNA level in non-alcoholic fatty liver (NAFL) patients with different liver fibrosis scores compared to healthy controls." (PMID 36718239, 2022). "It was reported that TLR9 knockout mice demonstrated less, or even protected from, liver fibrosis than controls." (PMID 36319750, 2022). "TLR9 upregulates HSCs under the influence of host origin DNA from apoptotic DNA, enhancing liver fibrosis." (PMID 34071550, 2021). "Kupffer cells can also be activated by TLR9 recognition of CpG-DNA and secreting IL-1β, reducing the degradation of the extracellular matrix, and promoting liver fibrosis." (PMID 33193293, 2020). "TLR9, which is activated by bacterial DNA, is also required for liver fibrosis through the induction of IL-1β, which in turn activates the IL-1 receptor on HSCs, resulting in their activation." (PMID 28761060, 2017). "The participation of TLR9 during liver fibrosis has been demonstrated in several mouse models of liver fibrosis, such as CCl4 and BDL models, in which TLR9-deficient mice exhibited significant reductions in liver fibrosis." (PMID 24904576, 2014). "Endogenous DNA from damaged hepatocytes is reported to enhance HSC activation through TLR9, thereby promoting liver fibrosis." (PMID 24904576, 2014). "TLR ligands can directly target HSCs via binding to TLR9, followed by inhibition of hepatic stellate cell chemotaxis and induction of their activation, ultimately leading to liver fibrosis." (PMID 24340043, 2013). "To address these points, we first reproduced the reported attenuation of hepatic fibrosis in TLR9-/- rodents as compared with WT." (PMID 24340043, 2013). "This study demonstrated the important features of TLR9 and DCs in liver fibrosis using CD11c-depleted mice." (PMID 20706677, 2010). "In previous study, decreased LPS production from the gut by OCA treatment activated TLR-4 and TLR-9, thus promoting inflammation, steatosis, and fibrosis, which might have contributed to reduced liver fibrosis." (PMID 35770078, 2022).
liver fibrosis (continued). "However, the mRNA level of TLR9 was significantly elevated in correlation with hepatic fibrosis progression in NAFL patients compared to healthy controls (P<0.05)." (PMID 36718239, 2022). "This process activates Kupffer cells through activation of TLRs (TLR4 and TLR9), which may also contribute to steatosis and hepatic fibrosis via stimulation of TLR9-dependent profibrotic pathways in mouse models." (PMID 32974366, 2020). "Moreover, attenuated hepatic fibrosis in TLR9-/- animal models supported the pro-fibrogenic effect of TLR9 activation." (PMID 24340043, 2013). "TLR9 expressed by HSCs is required for HSCs activation by both TLR9 agonists (CpG) and apoptotic hepatocyte DNA, and is thought to contribute to the development of liver fibrosis." (PMID 24340043, 2013). "Disruption of TLR9, MyD88, or IL-1β signaling significantly attenuates liver fibrosis." (PMID 24340043, 2013). "TLR9−/− mice showed a reduction of liver fibrosis after BDL and chronic CCl4 treatment." (PMID 20706677, 2010). "In addition to TLR4, HSCs also express TLR3 and TLR9, which are related to liver fibrosis." (PMID 34071550, 2021). "Accumulation of cytosolic DNA due to reduced DNase II activity triggers aberrant TLR9 signaling, upregulating IFN‐β expression and inducing RIPK1‐dependent necroptotic hepatocyte death, thereby driving liver fibrosis and NAFLD." (PMID 39158380, 2025). "This curcumin anti-hepatic fibrosis efficacy can be attributed to its inhibitory role through a direct binding to fibrosis-mediating proteins such as PDGFRB, Timp-1, TLR-9 and TGF-β." (PMID 36319750, 2022). "In liver fibrosis model mice with TLR9-knockout, the expression of a-SMA in the liver is down-regulated, indicating that TLR9 can promote liver fibrosis." (PMID 33193293, 2020). "As a preliminary study, our data showed a correlative overexpression of TLR9 mRNA with hepatic fibrosis progression in NAFL patients without the effectiveness of TLR9 gene polymorphisms." (PMID 36718239, 2022). "On the other hand, TLR9-/- fibrotic recipients reconstituted with TLR9-/- or WT lymphocytes showed no changes in severity of hepatic fibrosis or serum ALT levels." (PMID 24340043, 2013). "TLR9-/- fibrotic recipients reconstituted with TLR9-/- or WT lymphocytes showed no changes in hepatic fibrosis severity or ALT serum levels." (PMID 24340043, 2013). "In addition, TLR9 expressed on HSCs can also be activated by DNA fragments released from hepatocytes, which aggravates the progression of liver fibrosis, while TLR3 and TLR7 signaling could impede liver fibrosis progression." (PMID 35990625, 2022). "Despite the inflammatory role of TLR9 in human NASH, TLR9 KO failed to improve hepatic fibrosis in murine NASH models." (PMID 31717860, 2019).